OVOL3 (ovo like zinc finger 3)
Description:
May act as a transcription regulator.
Synonyms: HOVO3
Tractability: No criterion of Open Targets' tractability assessment is met for any kind of drug.
Gene: Protein-coding gene on chromosome 19 (36,111,116 to 36,113,711, forward strand). Ensembl gene ENSG00000105261.
Subcellular location: Nucleus
Subcellular location (Human Protein Atlas): Nucleoplasm; Cytosol; Vesicles
Gene Ontology:
Molecular function: DNA-binding transcription factor activity, RNA polymerase II-specific; RNA polymerase II cis-regulatory region sequence-specific DNA binding; DNA binding
Biological process: epidermal cell differentiation; regulation of transcription by RNA polymerase II; negative regulation of cell differentiation; negative regulation of multicellular organismal process; negative regulation of signal transduction; regulation of keratinocyte differentiation; regulation of keratinocyte proliferation
Cellular component: chromatin; nucleus
Genetic constraint (gnomAD): Loss-of-function variants: 22 observed, 19.13 expected, observed/expected ratio (o/e) 1.15, 90% interval 0.82 to 1.63. The upper end of that interval is the gene's LOEUF score, 1.63, which puts it in group 6 of 6, group 1 being the genes least tolerant of losing a copy. Missense variants: 290 observed, 278.83 expected, observed/expected ratio (o/e) 1.04, 90% interval 0.94 to 1.15. Synonymous variants: 102 observed, 105.08 expected, observed/expected ratio (o/e) 0.97, 90% interval 0.83 to 1.14.
Homologues: Orthologues: chimpanzee OVOL3 (100% identical), macaque OVOL3 (98% identical), rabbit OVOL3 (92% identical), dog OVOL3 (89% identical), guinea pig OVOL3 (89% identical), pig OVOL3 (89% identical), mouse Ovol3 (86% identical), rat Ovol3 (85% identical), zebrafish ovol1a (51% identical), zebrafish ovol1b (47% identical), Caenorhabditis elegans lin-48 (42% identical), Drosophila melanogaster CG12391 (24% identical), and 5 more. Paralogues in human: OVOL2 (51% identical), OVOL1 (49% identical), ZNF641 (29% identical), ZSCAN32 (26% identical), ZKSCAN2 (25% identical), ZSCAN5A (25% identical), ZSCAN5C (25% identical), ZSCAN29 (25% identical), ZNF274 (24% identical), ZNF496 (24% identical), ZBTB35 (23% identical), PEG3 (23% identical), and 17 more.
Diseases named in the same sentence as OVOL3 in open-access papers:
OVOL3 is named in the same sentence as 1 disease in open-access papers, as found by Europe PMC text mining. Sharing a sentence is not in itself a finding about the gene and the disease.
OVOL3 shares sentences with these, for which no sentence is quoted: breast carcinoma (1 paper).